CTSK (cathepsin K)
Diseases named in the same sentence as CTSK in open-access papers (continued):
Sharing a sentence is not in itself a finding about the gene and the disease.
renal cell carcinoma (continued). "Moreover, in TFEB-rearranged renal cell carcinoma, cathepsin K and melanogenesis markers are constantly positive, whereas TFE3-rearranged renal cell carcinoma stains for cathepsin K in roughly half of the cases, HMB45 in 8% and Melan-A in 22%." (PMID 35980471, 2022). "CTSK has been investigated in the primary kidney cancers of primary or transplanted kidneys in patients, and the study regarding urology experts performed a histological examination of renal cell carcinoma, and they also included CTSK as one of the immunodiagnostic signs." (PMID 36005209, 2022). "In conclusion, since TFE3/TFEB-rearranged renal cell carcinoma may mimic several histotypes, an immunohistochemical panel to differentiate them from common renal cell tumors should include cathepsin K, CA9, CK7, and parvalbumin." (PMID 35980471, 2022). "Cathepsin K is a valuable marker in the differential diagnosis of renal cell carcinoma." (PMID 34069976, 2021). "Conversely, cathepsin K is unevenly observed in TFE3-rearranged renal cell carcinomas." (PMID 34069976, 2021). "As the target DNA sequences of MiTF overlap with those of TFE3 and TFEB, it has been hypothesized that the overexpressed TFE3 fusion proteins or native TFEB in these renal cell carcinomas may have the same effect on the promoter of cathepsin K." (PMID 34069976, 2021). "Interestingly, PRCC-TFE3 renal cell carcinoma is labelled more frequently for cathepsin K than ASPL-TFE3 renal cell carcinoma." (PMID 31382581, 2019). "These tumors demonstrate similar immunohistochemistry results to TFEB translocation renal cell carcinoma, commonly expressing pigment differentiation-related markers (Melan-A, HMB45, and cathepsin k)." (PMID 38730456, 2024). "For example, the occurrence of an SFPQ::TFE3 translocation in a PAX8-positive renal tubular stem cell will give rise to renal cell carcinoma, which has a 78%, 38%, and 44% chance of staining for CD10, cathepsin K, and HMB45, respectively." (PMID 39410016, 2024). "Cathepsin K and parvalbumin are the two useful markers in the differential diagnosis between oncocytoma and TFE3/TFEB-rearranged renal cell carcinoma." (PMID 35980471, 2022). "Among the novel fusions, none of the NONO-TFE3 rearranged renal cell carcinomas have been shown to express cathepsin K, whereas RBM10-TFE3 rearranged renal cell carcinoma and some MED15-TFE3 rearranged renal cell carcinoma are reactive for this marker." (PMID 34069976, 2021). "The data of clinicopathologic features, TFE3 and cathepsin K IHC, PRCC-TFE3 FISH assay of PRCC-TFE3 renal cell carcinomas." (PMID 28949976, 2017). "Basically, translocation renal cell carcinoma is labeled for cathepsin K and HMB45 while it is negative for CA9 and CK7." (PMID 35980471, 2022). "Indeed, cathepsin K is expressed in roughly half of TFE3-rearranged renal cell carcinomas, and is observed in virtually all TFEB-rearranged renal cell carcinomas." (PMID 34069976, 2021). "Conversely to TFE3-rearranged renal cell carcinoma, pure epithelioid PEComa/epithelioid angiomyolipoma constantly express cathepsin K, regardless of the type of translocation." (PMID 34069976, 2021). "In addition to TFE3, cathepsin K also shows consistent diffuse positivity in ASPS, which is helpful for differential diagnosis against other tumors such as renal cell carcinoma, ASPCR1-TFE3 translocation renal cell carcinoma, adrenal cortex carcinoma, and paraganglioma." (PMID 41446840, 2025). "Notably, cathepsin K is expressed in approximately 60% of TFE3-rearranged renal cell carcinomas and is consistently negative in other common renal cell neoplasms." (PMID 39410016, 2024). "However, this explanation seems unlikely, because cathepsin K is ∼6 MB away from the breaking point in the PRCC-TFE3 rearranged renal cell carcinoma and cases negative for cathepsin K are recorded." (PMID 34069976, 2021).
renal cell carcinoma (continued). "Cathepsin K immunolabelling is not observed in the most common adult renal cell carcinomas (clear cell renal cell carcinoma, papillary renal cell carcinoma, and chromophobe renal cell carcinoma), but it is commonly detected in a subset of renal tumors, as illustrated below." (PMID 34069976, 2021). "On the other hand, cathepsin K is positive in TFEB-rearranged renal cell carcinoma and half of TFE3-rearranged renal cell carcinoma while it is negative in papillary renal cell carcinoma." (PMID 35980471, 2022). "Cathepsin K is positive in TFEB-rearranged renal cell carcinoma and half of TFE3-rearranged renal cell carcinoma while it is negative in chromophobe renal cell carcinoma." (PMID 35980471, 2022).
atherosclerosis (12 papers, 2010 to 2023). A disease characterized by the build-up of fatty material and calcium deposition in the arterial wall resulting in partial or complete occlusion of the arterial lumen. "Cathepsin-K (CatK)is a cysteine protease endowed with collagenase and elastase activities, whichhas recently been implicated in the pathogenesis of progressive atherosclerosis." (PMID 39077719, 2022). "Tissue proteases (cathepsins) show differential expression in various stages of atherosclerosis, and in vivo knockout studies revealed that deficiency of cathepsin K or S reduced atherosclerosis." (PMID 24170975, 2013). "For instance, we developed a novel integrin αvβ3 targeted and cathepsin K-responsive nanoparticle (T/R NPs) to control the release of rapamycin in atherosclerosis lesions." (PMID 36683743, 2023). "Cathepsin K can induce atherosclerosis by regulating the re-distribution of ECM, and its expression is regulated by the disturbed flow-mediated integrin-cytoskeleton-NF-κB signaling axis." (PMID 36683743, 2023). "Cathepsin-K (CatK) is a cysteine protease involved in vascularremodelling, as well as in progressive atherosclerosis." (PMID 39077719, 2022). "CTSK is mainly involved in the elastic intima's hydrolysis at the early stage of atherosclerosis, contributing to VSMCs proliferation." (PMID 35673565, 2022). "In conclusion, we have successfully engineered an integration of integrins αvβ3 targeting and CTSK responsive nanoparticles and demonstrated promising potential for atherosclerosis treatment." (PMID 35673565, 2022). "Foamy macrophages are known to produce MMP9 and cathepsin K in diseases including atherosclerosis, and MMP9 in multiple sclerosis." (PMID 31736973, 2019). "The expression of CTSS and CTSK (Cathepsin K) as well as their proteins in patients with atherosclerosis is significantly elevated, although the mechanism of CTSS in acute atherosclerotic cerebral infarction has not been studied yet." (PMID 30341237, 2018). "We first examined the expression of CTSK and integrin αv in atherosclerosis mice." (PMID 35673565, 2022). "The role of cathepsin K and foam cells in atherosclerosis has been demonstrated by others." (PMID 20409295, 2010). "Moreover, disruption of the cathepsin K gene reduces atherosclerosis progression suggesting the proteolytic activity of cathepsin K to be important for the pathogenesis of atherosclerosis." (PMID 20409295, 2010). "Moreover, other proteases such as cathepsin K are also involved in atherosclerosis development." (PMID 36683743, 2023). "In addition, local disturbed flow forms near the shoulder of the atherosclerotic plaque, which may further promote the expression of CTSK and aggravate atherosclerosis." (PMID 35673565, 2022). "Therefore, CTSK could be an ideal candidate to trigger drug release from nanocarriers in atherosclerosis lesions." (PMID 35673565, 2022). "Here, we reported a CTSK-sensitive nanoparticles drug delivery system that effectively targets atherosclerosis sites via αvβ3 and releases RAP in response to CTSK." (PMID 35673565, 2022). "Cathepsin K belongs to the family of lysosomal cysteine cathepsins; it is involved in the turnover of ECM proteins in many organs, and contributes to cardiovascular disease (including atherosclerosis and aortic aneurysms), inflammation, and obesity." (PMID 27069251, 2016). "Besides CTSK, other members of the cathepsin family, including cathepsin B (CTSB) 52, cathepsin S (CTSS) 53, cathepsin L (CTSL) 54, and cathepsin C (CTSC) 55, also play a critical role in the development of atherosclerosis." (PMID 35673565, 2022). "Similarly, the extent of atherosclerosis of other aorta sites, including AA, TA, abdominal aorta, and brachiocephalic artery, were evaluated by H&E staining, Masson's trichrome staining, and IHC (MMP-9, CTSK, CD68, and α-SMA)." (PMID 35673565, 2022).
osteosclerosis (12 papers, 2016 to 2025). Abnormally high bone density. "Deficiency of cathepsin K impairs bone resorption and further bone remodeling leading to progressive osteosclerosis and bone fragility." (PMID 40144453, 2025). "It is determined by a gene mutation leading to cathepsin K deficiency and predisposes a patient to osteosclerosis, resulting in increased bone fragility." (PMID 38731051, 2024). "Mice deficient in cathepsin K had osteosclerosis in the presence of fully differentiated osteoclasts while mice overexpressing cathepsin K had decreased trabecular bone volume and increased bone turnover." (PMID 26892377, 2016). "When CTSK is knocked out in mice, osteoclast bone resorption is reduced, thereby increasing bone formation by affecting the RANKL/OPG signaling pathway of osteoblasts, however, its knockdown may also contribute to the development of osteosclerosis." (PMID 36210855, 2022).
gastric cancer (11 papers, 2012 to 2024). A primary or metastatic malignant neoplasm involving the stomach. "The results confirm that CTSK is a promising predictive target related to the TME of gastric cancer, and that its expression not only predicts patient prognosis but also provides new strategies for immunotherapy of tumor." (PMID 37930479, 2023). "KT regulated the expression of the calcyclin-binding protein (CYBP) and cathepsin K. CYBP has been reported as a negative regulator of malignant behavior in gastric cancer and metastasis in colon cancer." (PMID 36674719, 2023). "CTSK promotes metastasis of gastric cancer cells by potentiating remodeling of ECM through activation of MMP5." (PMID 37198626, 2023). "Taken together, these results suggest that MMP-9, TIMP-2 and cathepsin K at least partially contribute to coronin 3-mediated gastric cancer metastasis." (PMID 22974233, 2012). "In the present study, we have provided clear evidence that coronin 3 is highly expressed in metastatic gastric cancer tissues and that coronin 3 can promote gastric cancer metastasis, at least in part by up-regulating cathepsin K and MMP9 expression and down-regulating TIMP2 expression." (PMID 22974233, 2012). "Cathepsin-K (CTSK) is overexpressed in Gastric cancer (GC) and the mechanism of its overexpression in GC is still unclear." (PMID 37930479, 2023). "The role of cathepsin K (CTSK) expression in the pathogenesis and progression of gastric cancer (GC) remains unclear." (PMID 38856944, 2024). "For gastric cancer in particular, CORO3 has been observed to promote cancer metastasis by upregulating the expression levels of MMP9 and cathepsin K." (PMID 34026752, 2021). "After meta-analysis of GC gene expression profile chip, it was found that 7 of these genes, including AKR1B1, CTSK, MMP2, TLR4, ADRB2, PDE1C, and PTGER3, had significant differences in gastric cancer tissues." (PMID 34646828, 2021). "For example, it promotes gastric cancer metastasis via interaction with Arp2, MMP-9, and cathepsin K, increases matrix degradation and invasion and decreases adhesion and formation of invadopodia-like extensions in glioblastoma cells." (PMID 34179087, 2021). "PLAU and CTSK have been shown to play a role in various tumors, with PLAU being considered as a potential biomarker in head and neck squamous cell carcinoma, promoting the EMT process, and tumor development in gastric cancer by cooperating with FOXM1." (PMID 38077303, 2023). "For instance, CORO3 depletion could suppress gastric cancer metastasis by reducing the expression levels of matrix metallopeptidase 9 (MMP9) and cathepsin K." (PMID 34026752, 2021). "Moreover, overexpression of coronin-1C was found to correlate with lymph node spread and increased clinical stage in gastric carcinoma, possibly via the regulation of MMP-9 and cathepsin K." (PMID 28302118, 2017). "Therefore, we examined the effect of coronin 3 knockdown or up-regulation on the expression of MMP-9, cathepsin K (based on the results of the PCR array), MMP-2, TIMP-1 and TIMP-2 in gastric cancer after infection." (PMID 22974233, 2012). "In conclusion, these results suggest that coronin 3 may promote the invasion and metastasis of gastric cancer both in vitro and in vivo by regulating the expression of MMP-9 and cathepsin K." (PMID 22974233, 2012).
lung fibrosis (9 papers, 2005 to 2025). "Cathepsin K is expressed in lung tissue and has been implicated in lung fibrosis." (PMID 21627832, 2011). "Mechanistically, CTSK activates a vicious cycle of collagen production in pulmonary fibrosis, highlighting its regulatory role and potential as a therapeutic target." (PMID 40605618, 2025). "CTSK displays potent endoprotease activity against fibrinogen, and the expression level of CTSK was up-regulated in the silica induced pulmonary fibrosis model." (PMID 34476240, 2021). "Recent reports from our group showed that cathepsin K plays a pivotal role during bleomycin-induced lung fibrosis." (PMID 18638383, 2008). "Due to its potent collagenolytic activity, cathepsin K, a lysosomal cysteine protease is an interesting target molecule with therapeutic potential to attenuate bleomycin-induced pulmonary fibrosis in mice." (PMID 18638383, 2008). "Moreover, TGFβ1 was inversely correlated with CTSK expression during silica-induced lung fibrosis in mice." (PMID 33445732, 2021). "We here tested the hypothesis that over-expression of cathepsin K in the lungs of mice is protective in bleomycin-induced pulmonary fibrosis." (PMID 18638383, 2008). "Over-expression of cathepsin K reduced lung collagen deposition and improved lung function parameters in the lungs of transgenic mice, thereby providing at least partial protection against bleomycin-induced lung fibrosis." (PMID 18638383, 2008). "Based on these observations, we hypothesized that over-expression of cathepsin K in the lungs of mice would ameliorate lung fibrosis and lung resistance in mice challenged with bleomycin." (PMID 18638383, 2008). "Excessive CTSK accumulation interacts with SNX9 to enhance TGF‐β1‐induced SMAD3 activation and GLS1 expression in fibroblasts, driving glutamine metabolism for collagen biosynthesis and exacerbating pulmonary fibrosis." (PMID 40605618, 2025). "By one week post-bleomycin treatment, wild-type mice and cathepsin K transgenic mice were found to develop early perivascular and peribronchial lymphohistiocytic infiltrates with significantly increased lung fibrosis developing in the wild-type but not cath K tg mice." (PMID 18638383, 2008). "Thus, as opposed to human or murine lung fibroblasts or human bronchial epithelial cells, type II epithelial cells do not appear to contribute to cathepsin K-dependent collagenolytic activities in bleomycin-induced lung fibrosis." (PMID 18638383, 2008).
PEComas (9 papers, 2012 to 2025). "HMB-45 (more specific) and Cathepsin K (more sensitive) are expressed in virtually all PEComas, ranging from diffuse staining to isolated positive cells." (PMID 40647483, 2025). "Among these transcribed proteins it is certainly to mention cathepsin K, a lysosomal cysteine protease encoded by the CTSK gene located on chromosome 1q21.3, which is highly expressed in all PEComas arising in and outside the kidney." (PMID 39410016, 2024). "Others are mesenchymal neoplasms known as PEComas, characterized by the presence of epithelioid cells co-expressing smooth muscle actin, cathepsin-K, melanogenesis markers, and sometimes melanin pigment deposition." (PMID 39410016, 2024). "The others are mesenchymal neoplasms known as PEComas, characterized by epithelioid cells co-expressing smooth muscle actin, cathepsin-K, melanogenesis markers, and sometimes melanin pigment deposition." (PMID 39410016, 2024). "The immunohistochemical analysis of renal TFE3-rearranged PEComas consistently shows a robust expression of cathepsin K (99%) and melanogenesis markers (HMB45 91% and MART1/MELAN A 80%) along with negativity for PAX8, cytokeratins, and S100." (PMID 39410016, 2024). "More recently, Cathepsin K was reported as a potential new useful IHC marker since it is expressed in most visceral PEComas." (PMID 34680376, 2021). "In a study aiming to distinguish PEComas from uterine smooth muscle tumors, twenty-one uterine PEComas and 45 SMTs were analyzed for PNL2; HMB45, Melan-A, Cathepsin-K, Desmin, and h-Caldesmon." (PMID 38664269, 2024). "Overexpression of TFE3 mediates expression of cathepsin K, which may represent an IHC marker useful in the identification of TFE3-altered PEComas." (PMID 40900800, 2025). "Overexpression of TFE3, member of the microphthalmia transcription factors family (MiTF), mediates the expression of cathepsin-K, which might be another IHC marker helpful to diagnose TFE3-altered PEComas." (PMID 34680376, 2021).
postmenopausal osteoporosis (9 papers, 2013 to 2025). Metabolic disorder associated with fractures of the femoral neck, vertebrae, and distal forearm. "This suppression reduces the expression of key osteoclast markers like NFATc1 and cathepsin K, leading to increased bone density in ovariectomized rats, a common model of postmenopausal osteoporosis." (PMID 40243497, 2025). "A recent randomized clinical trial evaluating odanacatib, a CTSK inhibitor developed for postmenopausal osteoporosis, has found that inhibition of the target lowered primary endpoints, but increased the risk of stroke (HR 1.32, P = 0.03)." (PMID 35246263, 2022). "Inhibitors of cathepsin K have shown promising results in clinical trials for postmenopausal osteoporosis, indicating that these drugs may soon become commercially widely available." (PMID 23951042, 2013). "Odanacatib is the only candidate CTSK inhibitor for human use, which is supported by the results from Phase III clinical trials, and exhibits high therapeutic efficacy in postmenopausal osteoporosis patients." (PMID 33553146, 2020). "ONO-5334, a low-molecular-weight synthetic inhibitor of cathepsin K, has been shown to increase areal BMD at the hip and spine in postmenopausal osteoporosis." (PMID 32117071, 2020). "During the process of postmenopausal osteoporosis, the reduction of BMD and deterioration of the bone microarchitecture in the femur were always accompanied by significant changes in the bone remodeling markers including ALP, BGP, TRAP, cathepsin K and DPD." (PMID 31216684, 2019).